MDM2 (MDM2 proto-oncogene)
Diseases named in the same sentence as MDM2 in open-access papers (continued):
Sharing a sentence is not in itself a finding about the gene and the disease.
mesothelioma (continued). "MDM2 3′-UTR is edited in all TCGA mesothelioma samples according to the TCEA." (PMID 33050791, 2020). "Specifically, MDM2 expression or the presence of the MDM2 SNP309 polymorphism, which causes increased expression of the MDM2 gene, correlated negatively with outcome in patients with mesothelioma." (PMID 30018737, 2018). "Finally, AGS significantly inhibited tumor progression in a xenograft mouse model of mesothelioma, confirming also in vivo that MDM2 could act as molecular player responsible for the AGS antitumor effect." (PMID 36672146, 2023). "We verified that in both cell lines MDM2 and JUN followed the same expression pattern previously observed in mesothelioma cells." (PMID 36672146, 2023). "However, Southern blot analysis for mdm2 indicated that no amplification had occurred in 18 mesothelioma cell lines tested." (PMID 8932331, 1996).
nasopharyngeal carcinoma (16 papers, 2010 to 2025). A carcinoma arising from the nasopharyngeal epithelium. "But when NOLC1 expression is down-regulated under the interference of shNOLC, the expression of MDM2 proto-oncogene is inhibited while the expression of the apoptosis-related genes (such as TNF-α) were up-regulated in nasopharyngeal carcinoma (NPC) cells." (PMID 34837693, 2021). "In nasopharyngeal carcinoma, NOLC1 and tumor protein 53 synergistically co-regulated a cellular proto-oncogene MDM2, leading to cell growth and reduction of apoptosis." (PMID 30505321, 2018).
chronic myeloid leukemia (15 papers, 2012 to 2025). "KEGG pathway analysis revealed that four hub genes- ABL1, HDAC1, HDAC2 and MDM2 - were primarily associated with chronic myeloid leukemia (KEGG:05220 and P = 3.27E-08) and notch signaling pathway (KEGG:04330 and P = 2.38E-04)." (PMID 38832038, 2024). "Among them, chronic myeloid leukemia may be associated with MDM2 abnormalities." (PMID 29221148, 2017). "KEGG analysis in the BaF3-T315 cells showed that the chronic myeloid leukemia signaling pathway (genes such as Cdk4, Tgfbr1, Gadd45b, Mdm2, Gadd45g, Polk, Rb1, Ctbp1, and Cdkn2a were enriched) was involved in the I13 treatment." (PMID 37124196, 2023).
esophageal squamous cell carcinoma (14 papers, 2010 to 2025). Esophageal squamous cell carcinoma (ESCC) is a type of esophageal carcinoma (EC) that can affect any part of the esophagus, but is usually located in the upper or middle third. "Previously, we conducted an updated meta-analysis to explore the impact of MDM2 (MDM2 Proto-Oncogene) polymorphisms on SCC susceptibility and found that the GG genotype of MDM2 rs2279744 polymorphism may be associated with an increased risk of esophageal SCC in Asian populations." (PMID 29743817, 2018). "Exemplary, the occurrence of MDM2 amplification correlated with worse overall survival in non-small lung cancer and esophageal squamous cell cancer." (PMID 41299419, 2025). "It has also been reported that autoantibody to MDM2 can be found in patients with esophageal squamous cell carcinoma." (PMID 26090506, 2015). "For instance, ATF3 was found to be down-regulated in esophageal squamous cell carcinoma (ESCC) lesions, and forced expression of ATF3 led to decreased growth and invasive properties of ESCC cells in vitro and in vivo through regulation of MDM2 expression." (PMID 32373541, 2020).
squamous cell carcinoma (14 papers, 2009 to 2023). A carcinoma arising from squamous epithelial cells. "Change in MDM2 expression is also associated with a poorer prognosis in the squamous cell carcinoma of the tonsillar region." (PMID 36551770, 2022). "Modification in MDM2 concentration is also related to a poorer prognosis in squamous cell carcinoma of the tonsillar region." (PMID 37185737, 2023). "The overexpression of the MDM2 protein was also demonstrated in head and neck squamous cell carcinoma, laryngeal cancer and squamous cell carcinoma of the tonsillar region." (PMID 38002053, 2023). "In squamous cell carcinoma (SCC), as the rs2228000, rs2228001 (XPC), rs2273953 (TP73), rs2279744 (MDM2), rs2299939 (PTEN) and rs8178085, rs12334811 (DNA-PKcs) affected the sensitivity to chemotherapy, so did the rs8178085, rs12334811 to radiotherapy." (PMID 27246533, 2016).
triple-negative breast carcinoma (14 papers, 2017 to 2025). An invasive breast carcinoma which is negative for expression of estrogen receptor (ER), progesterone receptor (PR), and human epidermal growth factor receptor 2 (HER2). "Several designated MDM2 PROTACs have already entered early phase clinical trials and preliminary data showed on-target anti-tumor efficacy in triple negative breast cancer." (PMID 39543744, 2024). "Additionally, we demonstrated that knockdown of MDM2 inhibits triple negative breast cancer MDA-MB-231 and T47D cell metastasis in a xenograft model." (PMID 40626562, 2025). "Notably, a recent study demonstrated that Ganoderic acid D overcomes gemcitabine resistance by promoting the degradation of HIF-1α driven by MDM2, which leads to a reduction in glycolysis in triple-negative breast cancer cells." (PMID 40046748, 2025). "Our preliminary data with the triple negative breast cancer (TNBC) cell line MDA-MB-231 suggests no influence of MDM2 on proliferation in the absence of receptor signaling." (PMID 28615518, 2017). "This idea was supported by data about MDA-MB- 231, triple negative breast cancer cell line, that Fulvestrant has no MDM2 effect on proliferation in the absence of estrogen receptor activation, which confirms that alizarin mainly works by cutting off estrogenic signals." (PMID 40580306, 2025). "Our group has recently reported that triple negative breast cancer (TNBC) metastasis is dependent on both MDM2 and MDMX, and depleting MDM2 results in increased MDMX, but depleting MDMX does not cause an increase in MDM2." (PMID 31489110, 2019).
viral infection (14 papers, 2012 to 2024). "Notably, PRV infection attenuated the interaction between TRPML1 and MDM2, suggesting that the viral infection impeded their interactions to prevent TRPML1 ubiquitination." (PMID 38295116, 2024). "Altered splicing pattern of MDM2 upon viral infection could be another factor contributing to reovirus oncolytic activity and a possible new target to further optimize its therapeutic potential." (PMID 27598998, 2016). "We did identify 294 DML sites in CD4+ T lymphocytes that were associated with AHI at host genes such as EZR, MDM2, and PIK3C2A that play a role in viral activity suggesting that HIV-1 may be modifying CD4+ T lymphocytes DNA methylation states to promote viral infection and replication." (PMID 34388205, 2021). "Taken together, these results indicated that viral infection inhibited the interaction between TRPML1 and MDM2, leading to the stabilization of TRPML1, an effect that was counteracted by P4." (PMID 38295116, 2024).
angiosarcoma (13 papers, 2012 to 2026). A malignant tumor arising from the endothelial cells of the blood vessels. "Histopathological analysis revealed positivity for vascular endothelial markers (CD31, ERG, factor VIII) and absence of MDM2 expression, confirming the diagnosis of angiosarcoma." (PMID 42131296, 2026).
medulloblastoma (13 papers, 2011 to 2025). A malignant, invasive embryonal neoplasm arising from the cerebellum. "Significantly, loss of MDM2 in Ptch1+/− mice, a model for Shh-mediated human medulloblastoma, impedes cerebellar tumorigenesis." (PMID 21437245, 2011). "In cell lines of medulloblastoma origin, MDM2 showed the largest difference in dependency score with negative regulators PPM1D, USP7 and MDM4, ranked 6, 41 and 64, respectively." (PMID 34885154, 2021). "Our results point to MDM2 as an important mediator of Shh signaling that may contribute to human medulloblastoma and its treatment." (PMID 21437245, 2011).
neutropenia (13 papers, 2018 to 2025). A decrease in the number of neutrophils found in the blood.